Y_RNA (Y RNA )
Gene: Miscellaneous RNA gene on chromosome 6 (149,631,437 to 149,631,549, forward strand). Ensembl gene ENSG00000207292.
Homologues: Orthologues: chimpanzee Y_RNA (99% identical), macaque Y_RNA (91% identical). Paralogues in human: RNY1 (92% identical), Y_RNA (89% identical), RNY1P8 (88% identical), Y_RNA (88% identical), RNY1P11 (88% identical), Y_RNA (87% identical), Y_RNA (86% identical), Y_RNA (85% identical), RNY1P7 (84% identical), Y_RNA (84% identical), RNY1P10 (83% identical), Y_RNA (83% identical), and 98 more.